CD4 (CD4 molecule)
Diseases named in the same sentence as CD4 in open-access papers (continued):
Sharing a sentence is not in itself a finding about the gene and the disease.
tumor (continued). "Tumour hypoxic zones recruit some immunosuppressive cells, such as bone marrow-derived suppressor cells (MDSCs), tumour-associated macrophages (TAMs) and Tregs, and thereafter inhibit the activation of CD8+ T and CD4+ T cells." (PMID 34868920, 2021). "Infiltration of CD8+ T cells was remarkably low in RKO, although the number of CD4+ T cells was comparable to that in other tumor cell lines." (PMID 34702924, 2021). "Compared with MDSCs from spleen of TB mice, tumor tissue-derived MDSCs had stronger suppressive effects on the proliferation of CD4+ T cells." (PMID 33717204, 2021). "Sections of tumor tissue stained by immunofluorescence revealed high levels of infiltrating CD4+ and CD8+ T cells in the Vaccine/Bintrafusp/SX group that were distributed uniformly throughout the tumors, compared to the other groups." (PMID 33669155, 2021). "A total of eight hub genes were positively correlated with SKCM tumor purity, and 10 hub genes were negatively correlated with the infiltration level of CD4+ T cells and B cells." (PMID 34722301, 2021). "Transcriptomics analysis of various CD4+ T cell subsets from patient tumours, normal surrounding tissue and peripheral blood revealed that tumour-localising Tregs have unique signatures of upregulated genes including pak2." (PMID 33573141, 2021). "In the rejection model, our data further indicated that survival time is significantly reduced when mice are depleted of TCRβ+ cells in general, evidencing a role for CD4+ T cells in the anti-tumour response." (PMID 33925140, 2021). "Correlation analysis indicated that CD4 and CD3E expressions were significantly associated with each other in the tumor tissues, suggesting the presence of tumor-infiltrating CD4+ T cells." (PMID 33968044, 2021). "Higher numbers of mature DCs, CD4+ T cells, and CD8+ T cells were present in tumor sites of IL-6 deficient mice compared with wild-type mice, thus underlining the pivotal role of IL-6 in tumorigenesis." (PMID 34671021, 2021). "Prior to ACT, tumor-specific CD4+ T cells were cultured in Th17 skewing conditions to produce IL-21, as we have previously published." (PMID 33809259, 2021). "The anti-tumorigenic properties of activin-A were mediated by the increased infiltration of effector CD4+ T cells in lung tumors, concomitantly with the diminished presence of Treg cells in the tumor microenvironment." (PMID 34548096, 2021). "The perfect peptide vaccine of the future—from our point of view—should include multiple peptides of different antigens combining CD4+ with CD8+ T cell epitopes as well as mutated and unmutated tumor-associated peptides." (PMID 33583769, 2021). "In contrast, the rSur-FLIPr-immunized mice injected with the anti-CD4 or isotype control antibodies still maintained the capacity of tumor growth inhibition." (PMID 34356870, 2021). "This highlights that the formation of immunosuppressive microenvironment occurs even at the onset of pancreatic tumorigenesis, and shows that CD8+ T cells mediated anti-tumor immunity during PDA initiation is negatively regulated by CD4+ T cells." (PMID 34290984, 2021). "Responses of CD8+ and CD4+ T cells against tumors are considered one of the principle mechanisms controlling tumor growth." (PMID 34234274, 2021). "Consistent with this, our flow cytometry analysis of tumor-infiltrating lymphocytes showed that there were significantly more CD4+, CD8+ T cells, and NK cells in the tumors of the rAAV-P2 treatment group than those compared to the control group." (PMID 34887423, 2021). "CD8+ and CD4+ cells within solid tumors can recognize neoantigens and can lead to an anti-tumor immune response in vivo." (PMID 34885082, 2021). "In contrast with anti-CTLA-4, PD-1 blockade exerts a limited impact on the on-treatment dynamics of tumor infiltrating CD4 + effector T cells in murine models." (PMID 33602280, 2021).
tumor (continued). "The importance of CD4+ T cells in a tumor immune response is gaining acceptance, and clinical trials and syngeneic mouse model studies have similarly identified distinct immune correlates." (PMID 33854497, 2021). "CD4+ T cells are a key component of tumor immunity via their communication with several types of immune cells, direct tumor killing and by providing support to CD8+ T cells." (PMID 33465095, 2021). "They further demonstrated that this population of CD44+ CD69+ CD62L− CD27lo T-bet+ CD4+ T cells conferred a protective benefit when transferred into treatment-naive tumour hosts." (PMID 32457487, 2021). "In the other nine tumors, CD11b cells were only detectable in the tumor stroma, with CD4 T cells in the majority of cases in the stroma as well (seven tumors only in the stroma and two tumors in the tumor cells and the stroma)." (PMID 34778030, 2021). "Consistently, BH4 supplementation (100 mg/kg−1/day, intraperitoneally) decreased tumor growth and increased tumor-infiltrating CD4+ and CD8+ T cells." (PMID 34502450, 2021). "There were significantly more MHC class IIhigh DCs that infiltrated into the tumor in mice treated with AAA-CD4+ T cells as early as 4 h after therapy, as compared to control mice (10-fold) and auto-CD4+ T cell-treated mice (3-fold)." (PMID 34625113, 2021). "As a part of their mechanism of action, these ICIs enhanced the activity of tumor-specific effector CD4+ and CD8+ T cells." (PMID 34944943, 2021). "But surprisingly, this combination therapy reshaped the immune microenvironment of tumor-bearing mice, including inhibiting the accumulation of MDSCs, promoting the proportion of M1 macrophages, CD4+ T and CD8+ T cells." (PMID 34858184, 2021). "Obviously, the cell subset of anti-tumor lymphocytes including activated dendritic cells (P = 0.009), activated CD4+/CD8+ T cells (P < 0.001), and effector memory CD8 T cells (P < 0.001) were enriched in the low-risk signature group." (PMID 34805135, 2021). "Through targeting PTEN, tumour-secreted miR-214 can promote CD4+ T cell differentiation into regulatory T cells (Tregs)." (PMID 34943783, 2021). "We used a systems biology approach to identify functional markers of a tumor-specific immune cell type, TI-Treg, based on the integrative analysis of three sets of CD4+ T cell transcriptome profiles from distinct biological contexts." (PMID 33598101, 2021). "CD4+ Tregs, one of the major Treg subtypes reported to date, can inhibit the tumour-specific T cell-mediated immune response and contribute to tumour escape and poor survival." (PMID 34461965, 2021). "Multiple preclinical studies have provided evidence that stimulation of GITR (TNFRSF18) in the tumor microenvironment contributes to costimulatory activation of CD4 and CD8 T-cells, while inhibiting/depleting intra-tumoral regulatory T cells." (PMID 32767058, 2021). "Immune cell subtypes evaluated within the inflammatory infiltrate in the tumor microenvironment focused on T cell subpopulations (CD4+, CD8+), total B cells (CD19+), and NK cells (CD56+)." (PMID 34692375, 2021). "We found that neoadjuvant chemotherapy promoted the infiltration of CD4+ GzmB+ T cells, B cells and granulocytes in the central region of the tumor, thus improving the tumor immune microenvironment." (PMID 34631551, 2021). "The majority of the neoantigen-specific immunity came from the CD4+ T-cells compartment, although two patients showed ex vivo neoantigen-specific killing of resected autologous tumour cells." (PMID 34065557, 2021). "For instance, IL-12 can cause CD4+ CD8+ cells to infiltrate and secrete various cytokines (e.g., IFN-γ) into the tumor microenvironment, which precipitates cascade reactions via other cytokines to elicit an antitumor effect." (PMID 33827606, 2021). "In this review, we discuss new developments detailing the multifaceted involvement of CD4+ T cells in the anti-tumour immune response and revisit older paradigms on the roles of CD4+ T cells in tumour immunity." (PMID 32457487, 2021).
tumor (continued). "We also characterized the tumor-infiltrating lymphocytes (TILs) in tumor tissue biopsies by studying several markers (CD4, CD8, FoxP3, CD20, PD-1, and PD-L1) through immunohistochemistry (IHC) staining." (PMID 34445631, 2021). "In our current study, we analyzed the ability of salt treatment to induce ex vivo expansion of tumor-primed CD4 (cluster of differentiation 4)+T cells to an effector phenotype." (PMID 33918403, 2021). "CD4+ T cells have been shown to undergo polarization into Th1 cells in order to help with the production of anti‐tumour effector cells, namely CTLs." (PMID 34262675, 2021). "Taking into consideration that activin-A administration in vivo considerably enhanced the infiltration of CD4+ T cells in the lungs of tumor-bearing mice, we next sought to characterize the profile of these cells." (PMID 34548096, 2021). "Along the perimeter of the RFA-treated tumor tissue they found intense infiltrations of CD4+ and CD8+ lymphocytes following resection." (PMID 34502076, 2021). "Collectively, these data suggest the importance of CD4+ T cells in the rejection of tumor cells after successful MBTA therapy." (PMID 34439097, 2021). "The ratio of CD8+T cells/CD4+T cells in the tumor microenvironment can reflect the specific immune responses to tumors." (PMID 34422050, 2021). "There were significant differences in tumor immune infiltrating cells, such as Macrophages M1, T cells CD4 memory activated, Mast cells resting, and Dendritic cells resting." (PMID 34635074, 2021). "Our principal finding is that while CD4+ and CD8+ TIL populations associate with improved OS in HNSCC, there was considerable heterogeneity in outcomes between different tumor anatomical subsites—previously unreported in the literature." (PMID 33668519, 2021). "They suggest that the anti-tumour CD4+ T cell response is inhibited and the suppressive Treg response is promoted in the TDLN, mimicking peripheral self-tolerance to tumour antigen." (PMID 34141724, 2021). "Analysis of lineage specific genes revealed differential methylation and gene expression in tumor CD4+ T-cells." (PMID 34012510, 2021). "•An increase in tumor purity was positively correlated with the expression of CDK-1 in COAD due to CD4+ cells and CDK-4 in COAD and READ resulting from a fraction of immune cells." (PMID 33732631, 2021). "The present findings demonstrate that a correlation exists between DPYSL2 expression and neutrophils, macrophages, CD4+ T cells, and dendritic cells in the tumor microenvironment of LUAD." (PMID 34517904, 2021). "Alphataxin, in combination with anti-PD-1 antibody, significantly elevated the ratio of circulating and tumor-infiltrating CD4+ T cells." (PMID 34900690, 2021). "In this context, as the parts of the cellular adaptive immune response, T helper cells (CD4+ T cells) and cytotoxic T lymphocytes (CTLs) inhibit tumor growth and development, while regulatory T cells (Tregs) promote tumor progression." (PMID 34572263, 2021). "In order to examine which cell type plays the critical role in the anti-tumor response, CD4+ and CD8+ T cells were depleted by specific antibodies in metastasis model, respectively." (PMID 34794428, 2021). "The analysis revealed that GNPNAT1 had a converse correlation with the infiltration of B cells, CD4+ T cells, and dendritic cells, which all had an anti-tumor effect in NSCLC." (PMID 33842535, 2021). "To study the relationship between PD-L1 expression and host antitumor immunity in the microenvironment, we next characterized the tumor immune cell infiltrate by immunohistochemical quantification of CD4+- and CD8+ T-cells." (PMID 33918309, 2021). "This reduced lactate production by tumor cells reshaped the tumor acidity, causing upregulation of IFN-γ + CD4 + T and IFN-γ + CD8 + T cells and reduction of Tregs, as well as upregulated pro-inflammatory and downregulated pro-tumorigenic cytokine levels." (PMID 34452627, 2021).
tumor (continued). "Strikingly, and consistent with the NY-ESO model, urelumab* treatment alone significantly reduced the number of CD8+ cells in the tumor compared to MCLA-145 and this was associated with an increase in the frequency of CD4+ T cells and PD-L1+ monocytes." (PMID 34290245, 2021). "The benefit of these ER interventions resulted from an enhanced infiltration of the tumor bed by activated CD8+ T cells, together with a concomitant reduction of regulatory CD4+ T lymphocytes from the tumor bed." (PMID 33809187, 2021). "The goals of cancer immunotherapy are to activate and expand tumor-specific CD4+ and CD8+ T cells as effective means of augmenting immunity to reduce tumor burden." (PMID 34493268, 2021). "Further, an efficient and durable CD4+ T cells-mediated tumor regression can be induced in vaccinated individuals." (PMID 33722265, 2021). "Since then a study reported tumor-specific CD8 T cells arose independently of CD4 T cells, but needed Th1-polarized CD4 T cells to effectively suppress tumorigenesis supporting the crucial role CD4 T cells play in tumor suppression by immunosurveillance." (PMID 34874009, 2021). "Another study found that tumor burden is associated with baseline T‐cell receptor β‐chain (TCRB) diversity, and that high diversity of TCRB increases the accumulation of CD4+ and CD8+ T cells." (PMID 34211459, 2021). "While CD4+ T cells support CTLs, these cells also have direct anti-tumor activity and can kill tumors through engaging p-MHC II and secretion of IFN-γ and TNF-α effector cytokines." (PMID 33708224, 2021). "We used CD8+ TILs as controls due to their widely accepted antitumor roles and compared with the transcriptome of CD4+ TILs due to their dual roles in tumor progression." (PMID 33916009, 2021). "Differentially expressed genes were identified by comparison of the expression profile in CD4+T cells isolated from tumor tissues and peripheral blood of TNBC patients respectively." (PMID 33301062, 2021). "In contrast, post-treatment differences were driven by the closer proximity of PD-1+ CD4+ T cells and tumor cells in responders (see red arrow), consistent with the increased immune activation gene score in responders relative to nonresponders." (PMID 34795254, 2021). "When comparing Q4 vs. Q1 in the tumor microenvironment for KK-LC-1, we see a greater proportion of M1 macrophages in Q4 tumors whereas there is a lower proportion of M2 macrophages and CD4+ T cells." (PMID 34917263, 2021). "Recent studies have found that LncRNA SNHG1 is highly expressed in CD4+ tumor-infiltrating lymphocytes of breast cancer and can inhibit the expression of miR-484." (PMID 34084160, 2021). "T helper 1 (TH1) cells represent a subset of the CD4 + T cell population that typically expresses high levels of interferon gamma, which acts to limit tumor growth, promote antigen presentation and active macrophages M1." (PMID 34952631, 2021). "It has been reported poly I:C can prolong the survival of CD4+ T cells and enhance the proliferation of activated T cells, and that it is involved in the reactivation of tumor-infiltrating CD8+ T cells." (PMID 34025640, 2021). "The addition of anti-CTLA-4 to CpG+OX40 has been shown to improve the abscopal response in a two-tumor A20 model by increasing the number of IFN-gamma producing CD4+ and CD8+ T cells and further decreasing the Treg frequency in the TME." (PMID 34868010, 2021). "Based on the differences in mean fluorescence intensity (ΔMFI), we observed higher expression for all ICs on tumor resident CD4+ and CD8+ TILs relative to the spleen." (PMID 33466653, 2021). "Th17 cells are a subset of pro-inflammatory CD4+ T cells that express RORγt and secrete the tumor-promoting cytokines IL-17 and IL-2216,21–29." (PMID 33972557, 2021). "CD4+CD25hi Forkhead-Box-Protein P3 (FoxP3)+ Treg cells are frequently found in the course of tumor progression and counteract APC activity, T cell activation, and anti-tumor functions of effector T cells (Teff)." (PMID 33430105, 2021).
tumor (continued). "Within the TME, pTregs are generated from naïve CD4+ T cells in response to tumor antigens and other stimulatory networks." (PMID 33532902, 2021). "For this, we examined the phenotype and function of tumor-infiltrating CD4+ T cells which cannot transduce activin-A signals through ALK4, during lung tumor development in vivo." (PMID 34548096, 2021). "This study showed increased numbers of CD8+ cells by IHC and decreased CD4+ CD25+ FoxP3+ Tregs in ER-tumours in mice treated with SERDs." (PMID 34602068, 2021). "For example, CD4+FoxP3+regulatory T cells (Tregs) are highly immunosuppressive, and often play a central role in driving tumor immune evasion and suppression of antitumor immunity." (PMID 33920168, 2021). "Genome wide DNA methylation landscape of tumor infiltrating and blood CD4+ T cells from glioblastoma patients revealed differentially methylation pattern." (PMID 34262562, 2021). "Confocal images showed both AAA-CD4+ T cells and auto-CD4+ T cells in the tumor of each treated mouse 24 h after injection." (PMID 34625113, 2021). "Meanwhile, they found that higher CD8+T and CD4+T infiltration corresponded to stronger tumor invasiveness and worse survival." (PMID 34925244, 2021). "Detecting a biomarker based on the spatial context of tumor and immune cells requires that malignant and reactive CD4+ T cells can be distinguished." (PMID 34795254, 2021). "Others have shown the synergistic anti-tumor effect of CpG+OX40 is due, in part, to CpG’s ability to increase OX40 expression on tumor infiltrating CD4+ T helper cells." (PMID 34868010, 2021). "Characterizing the higher-order tissue structure of the CTCL TME reveal topographical differences in effector PD-1+ CD4+ T cells, tumor cells, and immunosuppressive Tregs." (PMID 34795254, 2021). "Both of these cytokines induce Tregs and inhibit dendritic cell function to present tumor antigens to activate CD4+ and CD8+ T cells." (PMID 35096592, 2021). "The aim of this study is to decipher the role of activin-A in the regulation of CD4+ T cell-directed immune responses in the tumor microenvironment, during the development of murine lung tumors." (PMID 34548096, 2021). "Anti‐PD‐1 antibody treatment increased tumor T‐cell numbers and activation in this setting, likely by activating the 40% of tumor CD4+ T cells and 70% of tumor CD8+ T cells expressing PD‐1, a marker of T‐cell exhaustion." (PMID 33480449, 2021). "Preclinical and clinical trials using α-GalCer have shown that this therapy is safe, exhibits durable activation, and increases the number of iNKT, NK, tumor-specific, CD4+, CD8+ T, and B cells." (PMID 34737957, 2021). "As expected, higher percentage of infiltrated CD8+T cells while lower percentage of infiltrated CD4+T cells in tumor of the combination strategy were clearly observed comparing to the PBS, αPD1 or thiolated nano‐vaccine treatment alone." (PMID 33747739, 2021). "With context-dependent immune responses influenced by oncogenic drivers and the presence of inflammation, CD4+ T cells carried complex and important roles within tumor microenvironments." (PMID 33691689, 2021). "In silico cytometry showed that high MMP-11 expression was associated with low tumor antigenicity, reduced TILs, including CD8+ T cells, CD4+ memory T cells and memory B cells, and low activation of dendritic cells." (PMID 34038440, 2021). "This is consistent with the lower value of CD4/CD8 reported in some tumor literature implying a better prognosis." (PMID 34422839, 2021). "Tumor CD4+ and CD8+ T cells in PD‐1 antibody‐treated WT or p50(f/f);Lys‐Cre mice were examined by flow cytometry." (PMID 33480449, 2021). "Tregs (CD4+ CD25+ Foxp3+) are involved in tumor development and progression by inhibiting anti-tumor immunity in the TME." (PMID 34867958, 2021). "The increased tumor‐infiltrating CD4+ and CD8+ T cells were confirmed by immunohistochemistry (and Fig EV5E)." (PMID 33938620, 2021).